CD4 (CD4 molecule)
Diseases named in the same sentence as CD4 in open-access papers (continued):
Sharing a sentence is not in itself a finding about the gene and the disease.
infection (continued). "In contrast, CD2l°w CD4+ cells of HIV-1 patients with a progressive course of infection had higher p24 levels than CD2low CD4+ cells isolated from controllers." (PMID 28953327, 2017). "Following infection, huBLT mice generate human effector and central memory CD4+ and CD8+ T-cell responses reactive to peptides corresponding to both IE and pp65 proteins." (PMID 28428537, 2017). "tat/rev (multiply-spliced) RNA+ cells ranged from <0.01 to 6.4% (mean 2.0%) of memory CD4 T cells at 9-14d post-infection." (PMID 28654687, 2017). "In the early stages of infection, HIV-1 replicates in gut-associated lymphoid tissues, resulting in a rapid and massive depletion of mucosal CD4+ T lymphocytes." (PMID 28661459, 2017). "Following the clearance of infection, CD4 Tem modulate to Tcm and return to secondary lymphoid tissues." (PMID 28106821, 2017). "We used a CD4+ T-cell decline trajectory model to deduce the predicted year of actual infection and observed increasing trends of URFs in patients infected recent years." (PMID 28744024, 2017). "While infection caused a significant increase in the frequency of CXCR3+ CD4+ and CD8+ T cells in the spleen of control mice, bpV(phen) treatment completely abrogated the upregulation of CXCR3 on T cells following infection." (PMID 28710387, 2017). "Infective filarial larvae (L3) recruit tTreg and induce their premature proliferation at the site of infection, rapidly biasing CD4+ T cell responses toward a regulatory phenotype approximately 7 days postinfection." (PMID 28603524, 2017). "It suggests that much of HIV dynamics observed within peripheral blood, can be explained by infection within memory CD4+ T cells and the impact HIV has on their activation and proliferation." (PMID 29049331, 2017). "At an early stage of primary infection, about 50% of HCMV-reactive CD4+ T cells were long-term IL-7Rpos memory cells, while 6–12 months later, the frequency of these cells increased to 70%, approaching 100% in remote infections." (PMID 29112951, 2017). "Further expression analysis of cyclin F at mRNA and protein levels in infected CD4+ T cells confirmed its significant down-regulation with infection." (PMID 28184007, 2017). "While the bacteria were almost completely eradicated by CD8+ T cells on day 7 post infection, the bacterial load in the organs of CD4+ T cell recipients was reduced by trend compared to that of control animals at this point in time." (PMID 28222146, 2017). "It was further shown that while antibody production was required in the later stages of infection to fully clear the virus, CD4 cytotoxicity was required earlier in infection to control viral replication." (PMID 28167943, 2017). "Antigen-specific CD4 T cells play multiple key roles in immune responses to infection, vaccination, or self-antigen." (PMID 29065175, 2017). "Spleen CD4+ T-cell activation as measured by CD69 expression was also significantly diminished 12-days post infection." (PMID 28262829, 2017). "In patient SD1, there was a distinct cluster arising from the naive cell population, but the sequences from Tfh, GC Tfh, and memory cell populations interspersed, suggesting infection of naïve CD4+ T cells by a distinct quasi-species." (PMID 28484447, 2017). "The expression profiles from three independent infection experiments showed that more than a third of genes dysregulated in CD4 cells were also altered in CD8 T cells and vice versa." (PMID 28487311, 2017). "Depletion of type I IFN alone appeared to impact the numbers of CD4+ T cells, which were reduced in the spleen upon infection." (PMID 28811340, 2017). "The percentage of IL-10+CD4+ T cells in the spleen increased with both infection and bpV(phen) treatment." (PMID 28710387, 2017). "Our model can be used to determine the timing of infection for an infected individual based on individual parameters, monitored data on CD4 cell counts and viral loads." (PMID 28100241, 2017).
infection (continued). "We found clear alterations in the composition of T cells residing in the BM following infection, notably a dramatic increase in the frequency and number of CD4+ T cells displaying an “effector” phenotype and secreting high levels of IFNγ." (PMID 28671989, 2017). "We show that mice deficient for PTPN22 are able to control the virus 30 days after infection, show reduced weight loss, and generate higher numbers of LCMV-specific CTLs and CD4 T cells with heightened function." (PMID 28747914, 2017). "In the self‐resolutive Pcc model, six of 10 peptides tested elicited IFNγ/TNF‐producing CD4 responses at day 6 post‐infection (Fig EV2B)." (PMID 28935714, 2017). "R5 tropic envelopes almost exclusively establish infection and allow for the infection of activated effector memory CD4+ T cells, macrophages, and dendritic cells." (PMID 28264054, 2017). "Upon infection with PbA-infected red blood cells, the total number of CD4+ T cells increased in the blood and brain of both mouse strains." (PMID 28203236, 2017). "Together, these findings clearly show that PTPN22 inhibits pro-inflammatory virus-specific CD4 T cell responses during LCMV Cl13 infection." (PMID 28747914, 2017). "At 6 dpi, infection levels and CD4+ T cell counts were assessed relative to microbe-exposed mock controls." (PMID 28241075, 2017). "There was an accelerated response in the Ag85A group in terms of IL-17+ CD4 cells, with evidence for a secondary wave of Th17 responses on day 60 of the challenge infection." (PMID 29046306, 2017). "This spatial distribution remained consistent, even as human CD4+ andCD8+ T-cell levels changed during the course of infection." (PMID 28198699, 2017). "HLA-DQs belong to HLA class II molecules, which are expressed as cell-surface glycoproteins that present viral peptides to CD4+ T cells resulting in generating immunity against infection." (PMID 28761441, 2017). "Here, we observed differences in the expression of the co-inhibitory receptors PD-1 and CTLA-4 between CD4 T cells from acute and chronic phases of infection." (PMID 28114324, 2017). "CD4+ T-cells at these sites facilitate viral replication, are significantly depleted during untreated infection, and are slow to regenerate during cART treatment." (PMID 29284044, 2017). "We propose that these cells represent activated and resting infected CD4+ T-cells, respectively, and estimate that infection of resting cells represent ~4% of productive reverse transcription events in chronic infection." (PMID 28678879, 2017). "Virus specific CD4+ T cells were present at low frequencies for the first 4–5 days post infection before undergoing rapid clonal expansion and recruitment with peak numbers seen in the lungs at between 7 and 14 days post RSV infection." (PMID 28953978, 2017). "The frequency of BM CD4+ T cells capable of producing IFNγ within the total BM was very low (0.10% ± 0.05) in naive mice, but increased following infection (7.64% ± 3.57 of total BM cells)." (PMID 28671989, 2017). "There is a longer period of asymptomatic infection and slower decline in CD4 cell counts, thought to be secondary to lower levels of plasma viraemia." (PMID 28259182, 2017). "Consistently, more CD3+ CD4+ T cells, but not CD8+ T cells, were found to display an effector memory phenotype (CD3+CD4+CCR7−CD45RA−CD62L−) at day 11 post infection in the spleen of stat1loxP/loxP/Vav-cre mice." (PMID 28290449, 2017). "CD4 T cells play an important role in CD8 T cell exhaustion and mouse strain susceptibility to infection often differs based on their ability to mount an appropriate CD4 T cell response." (PMID 28715493, 2017). "CD8+ T cells, alongside CD4+ T cells and γδ T cells, are present at an increased frequency within the ileum of C. parvum-infected calves at day 3 post-infection, compared with tissues from uninfected calves." (PMID 28800747, 2017). "We obtained 530 million total CD4+ T cells from Participant A approximately 18 months following infection on ART." (PMID 29112956, 2017).
infection (continued). "We analyzed the proportion of classic CD4+CD25HighFoxP3+ Tregs expressing Helios and found an inverse correlation between Tregs expressing Helios and viral load in early infection (r = −0.63; p = 0.04)." (PMID 29246111, 2017). "In mice lacking B cells and CD8+ T cells, IFNγ is required for acute infection control, suggesting that it mediates the anti-viral effect of CD4+ T cells." (PMID 28394921, 2017). "The related collected factors included patient age, gender, marital status, infection route, baseline CD4 count, antiretroviral therapy regimens, time between HIV diagnosis and initiating antiretroviral therapy." (PMID 28187212, 2017). "In C57BL/6 adult mice, IFNγ-producing CD4+ T cells were essential in the initial phases of C. parvum infection to control the severity of infection, while IL-4-producing CD4+ T cells were important to accelerate resolution of infection." (PMID 29295550, 2017). "TLR2 is induced during infection and is important for DC activation, which influences the drive of naïve CD4+ T cells to the Th1 and Th17 pattern as well as the production of CXCL1." (PMID 28280488, 2017). "Accumulating studies have indicated that infections with pathogens such as human cytomegalovirus (CMV) and dengue virus (DENV) are associated with an expansion of CD4 TEMRA cells." (PMID 29133794, 2017). "The HIV receptor, CD4, is usually required for infection and is expressed on CD34+ HSPCs, although at low levels compared to CD4+ T cells." (PMID 28732051, 2017). "The higher percentage of IL-7Rpos HCMV-specific CD4+ T cells in NT women was observed also at 6–12 months after infection, although a smaller number of women were examined at this late time point." (PMID 29112951, 2017). "Identification of CD4+ T cell subpopulations expressing HIV-1 RNA transcripts after ex vivo infection of unstimulated PBMCs." (PMID 28698276, 2017). "Accordingly, a recent study demonstrated that granzyme B- and perforin-producing CD4+ T cells were able to recognize and kill influenza virus-infected cells at the site of infection." (PMID 28289418, 2017). "Very few HEL-specific CD4+ T cells had proliferated in the lymph nodes of sTg-IRBP:HELhi mice by day 7 post-infection compared to multiple rounds of proliferation noted in a proportion of the non-transgenic WT donor cells (data not shown)." (PMID 29079770, 2017). "In vitro infection of rhesus CD4+ T cells and in vivo infection of rhesus macaques revealed levels of viral replication of SIVmac239M comparable to parental SIVmac239." (PMID 28472156, 2017). "In contrast, infection of CD4+ T cells with IRF8-expressing retrovirus enhanced Th9 cell differentiation as demonstrated by increased production of IL-9 mRNA and protein without inducing transdifferentiation." (PMID 29233972, 2017). "In controlled-infection granuloma-like structures, the CD4+ T cells were somewhat more abundant during the 4th and 6th days postinfection, while CD8+ T cells were significantly reduced over time." (PMID 27799331, 2017). "Upon in vitro infection with HIV, productive infection of CD4+ T-cells takes place and leads to either cell lysis or giant cell/syncytia formation, in which both infected and uninfected cells fuse, leading to spread of infection." (PMID 28588579, 2017). "The transient recovery of CD4+ T cells is then followed by their gradual depletion and a progressive increase of viremia, which constitute the chronic phase of the infection." (PMID 28620380, 2017). "The early fast decay in viral load (including phase 1a and 1b) is most likely due to infection of activated CD4+ T-cells, which quickly progress to viral production." (PMID 28678879, 2017). "Although both infections manifest the same clinical spectrum, the much lower rate of CD4+ T-cell decline and slower progression of disease in HIV-2 infected individuals have grabbed the attention of several researchers." (PMID 28588579, 2017).
infection (continued). "As expected during the latency stage of infection (week 28 and onward), the majority of Hobit+ CD4+ T cells expressed an effector phenotype." (PMID 28392788, 2017). "This is perhaps unsurprising given that the predominant targets of infection are CD4+ T cells that lack FcγR expression (23, –, 25)." (PMID 27795431, 2017). "It has long been recognized that influenza virus-specific CD4(+) T cells are important in protection from infection through direct effector mechanisms or by providing help to B cells and CD8(+) T cells." (PMID 29358939, 2017). "The infected CD4+ T-cells result from the infection of both the wild and resistant type healthy CD4+ T-cells and die at a rate μII, and are killed by activated cytotoxic T-cells at the rate αIZa." (PMID 29349288, 2017). "Infection with a very low number of parasites would have made recovery of LLO-specific CD4+ T cells difficult." (PMID 29312315, 2017). "In this model, intranasal infection was significantly more effective at inducing CD4 CTL activity in the lung than intramuscular infection, even at substantially lower infectious doses." (PMID 28167943, 2017). "Ultimately, this means the relationship analyzed is between CD4 count and TB incidence either from primary progression, re-activation or re-infection." (PMID 29259846, 2017). "CD69 and CCR5 were upregulated early after infection on CD4+ T cells in all three animals, and α4β7 expression also increased in DF98 over time despite an initial drop." (PMID 29259582, 2017). "To see if SPgV pre-infection protected gut CD4+ T cells from SIV-mediated destruction, we collected colon pinch-biopsies from animals pre- and post-SIV infection, then analyzed the abundance of lamina propria CD4+ cells using immunohistochemistry (IHC)." (PMID 29073258, 2017). "In terms of total cells, despite the infection promoting CD4+ T Foxp3+ cells expansion on both infected groups at fourth wpi, it was reduced on infected A2AR−/− mice when compared to infected WT compared with respective non-infected littermate controls." (PMID 28775724, 2017). "Factors that impact on longevity include: the age at infection, the nadir CD4 cell count, the time spent with CD4 counts >500 cells/mm3, and other variables." (PMID 28893184, 2017). "Activated CD4 T-cells are also more permissive to infection and produce more virus than resting cells, with specific CD4 T-cell subsets being preferential HIV targets." (PMID 28893286, 2017). "It has been reported that HHV-6 infects monocytes and promyelocytes and that HHV-7 infects CD4+ T lymphocytes mainly; they tend to have a broader spectrum of infection following reactivation in response to stimuli." (PMID 28902907, 2017). "We have previously shown that multiple exposures to DENV increase the magnitude of CD4+ T cell DENV-specific responses relative to primary infection suggesting that infection history can influence magnitude of DENV-specific T cell responses." (PMID 29081779, 2017). "In the CD2+ CD4+ cell population, 2.24% were p24+ whereas infection rates of the CD2low CD4+ cells were with 10.33% nearly 5-times higher." (PMID 28953327, 2017). "In immunodeficient CB17 SCID mice R. typhi causes a 100% fatal infection and we show here that adoptively transferred CD8+ as well as CD4+ T cells that acquire a TH1 phenotype protect these animals from severe disease and death." (PMID 28222146, 2017). "IFNR blockade also increases total splenic T-lymphocyte and antiviral specific CD4 T-cell numbers during LCMVCL13 infection." (PMID 29301196, 2017). "About 50% of HCMV-reactive CD4+ T cells (median value) were IL-7Rpos one month after infection onset, and then increased until comprising virtually all of the circulating HCMV-specific CD4+ T cells in remote infections." (PMID 29112951, 2017). "Our studies suggest primary eEC in fact inhibit infection of CD4+ T cells, likely due to the antiviral factors they secrete." (PMID 28207890, 2017).
infection (continued). "Sexual transmission of HIV requires exposure to the virus and infection of activated mucosal immune cells, specifically CD4+ T cells or dendritic cells." (PMID 28743816, 2017). "In the peritoneal fluid, the highest number of CD4+ cells was found in rats in group G on day 7 post-infection; however, the number of CD8+ cells at the same time was significantly (p<0.05) lower than in group U." (PMID 28333957, 2017). "Meanwhile, the proportion of CXCR5+ CD4+ Tfh cells in splenic CD4+ T cells kept increasing rapidly from week 0 through week 7 after infection and decreased at 9 weeks post-infection, but continues to increase at 12 weeks post-infection." (PMID 29192177, 2017). "In pigs, only a few experiments identified CD8+ and CD4+CD8+ cells in the acute phase of the infection as the major source of the IFN-γ production." (PMID 28642841, 2017). "The P2X7 receptor was activated in CD4 T cells following the rupture of infected erythrocytes and these cells became highly responsive to ATP during acute infection." (PMID 28859168, 2017). "Our model can also be used to determine the timing of infection for an infected individual based on individual parameters, monitored data on CD4 cell counts and viral loads, which is difficult to get." (PMID 28100241, 2017). "Previous infection or repeated immunization led to competition for virus-specific CD4+ T cells limiting naive Tfh expansion, but inducing expansion of preexisiting, clonal populations that subsequently resided in a memory population of ICOS-CD38-cTfh." (PMID 29326687, 2017). "Together our findings underscore the delicate balance of CD4 T-cell responses required to mediate protection from infection and disease." (PMID 29097996, 2017). "Results showed that compared to naive mice, expansion of LLO-specific CD4+ T cell populations occurred significantly more in mice that received LdWTLLO infection." (PMID 29312315, 2017). "Another recent observation was that most microbe-specific naïve CD4+ T cells produce memory cells during infection." (PMID 28134792, 2017). "Similar patterns of CD4+ cell population changes were observed upon infection by both NDV AF2240 and IBS002." (PMID 28569155, 2017). "CD4 cells are important for control of primary infection, but there is less proliferation of CD4 than CD8 cells." (PMID 29375553, 2017). "Immunization prior to infection induced PmpG-specific CD4 cells in the iLN that produced significantly more IFN-γ only producing cells, multiple cytokine producing cells (IFN-γ, TNFα, and IL-17) and a central memory subset." (PMID 28106821, 2017). "Splenic CD4+ T cells isolated from hamsters with VL (28 days post-infection) showed marginal capacity to inhibit intracellular parasite growth in co-cultured in vitro infected macrophages." (PMID 28103263, 2017). "Similar to infection during or after HDM sensitization, infection prior to allergen exposure triggered airway infiltrations of CD4+ T cells secreting increased amounts of IL-17, IFN-γ, and IL-5." (PMID 29184554, 2017). "After the frequency of naïve CD4+ T cells had fallen to its lowest point 10 dpi, it quickly reached a higher and more steady level than the pre-infection level." (PMID 28232735, 2017). "At early stage of infection, the numbers of CD4+ T -cells (Ths) and CD8+ T-cells (Tcs) significantly increased at 10dpi." (PMID 29137226, 2017). "In both human and experimental models of cutaneous leishmaniosis (CL), control of the infection is mediated by the early induction of an IL-12 driven Th1 immune response along with the production of IFN-γ by CD4+ T cells." (PMID 27094260, 2017). "3pSIV infection showed significantly lower %CD4 at month 6 (p = 0.0441 by Mann-Whitney U-test) and shorter survival periods (p = 0.0049 by Log-rank test) than SIVmac239 in 90-120-Ia+ macaques." (PMID 28931083, 2017). "The detection of antigen-specific CD4 T cells represents a key challenge in detection of vaccine or infection-induced responses." (PMID 29065175, 2017).